MMP2 (matrix metallopeptidase 2)
Diseases named in the same sentence as MMP2 in open-access papers (continued):
Sharing a sentence is not in itself a finding about the gene and the disease.
tumor (continued). "The invasion and migration of tumor cells require alterations in cell polarization, activation of a group of matrix degrading enzymes, such as matrix metalloproteinases (MMP)-2 and -9." (PMID 30646538, 2019). "Several studies suggested that overexpression of MMP-2 and MMP-9, upon their role in OPN-induced tumor invasion, is associated with an aggressive phenotype of cancers." (PMID 31934533, 2019). "As MMP-2 and MMP-9 are key regulators of extracellular matrix (ECM) degradation and tumor invasion, CADM1 is therefore a metastasis susceptibility gene and is involved in the invasion-metastasis cascade in MM." (PMID 31334110, 2019). "Lidocaine reduced mean MMP-2 serum concentration 14 days post-tumour resection compared to sevoflurane: 1099 ± 787 pg mL−1 (mean ± SD) versus 1598 ± 586 pg mL−1, p = 0.044." (PMID 31546727, 2019). "By contrast, upon adding anti-CD73 neutralizing antibodies to co-cultured fibroblasts and tumor cells, MMP-2 production in the supernatant was clearly suppressed, compared with the control." (PMID 31510956, 2019). "In another study, a single injection of lentiviral vectors encoding Stat3-targeting shRNA were able to downregulate Stat3, Survivin, and MMP-2 at the same time impair tumor cell survival and invasiveness in melanoma models." (PMID 30847297, 2019). "In this study, a correlation was demonstrated between a higher expression of MMP-2 in tumor, compared to its expression in stroma among patients without metastases to lymph nodes." (PMID 31223594, 2019). "On the other hand, ~50% of the NSCLC patients revealed stronger upregulation of the MMP2 in the fibroblasts neighboring the lesion, than in the tumor itself." (PMID 31921636, 2019). "Current preclinical evidence further highlighted that decreasing MMP-2 activity by specific inhibitors led to attenuated angiogenesis and tumour progression." (PMID 30947736, 2019). "VCAM1 is one of five genes (CXCL12, MMP2, MMP11, VCAM1, and MME), which were associated with tumor progression, angiogenesis, and metastasis." (PMID 31731625, 2019). "Significant differences were observed regarding the MMP-2 expression in the tumor, and its level decreased with the increase in the stage of metastases in the lymph nodes (P=0.015)." (PMID 31223594, 2019). "MMP-2 plays a crucial role in extracellular matrix degradation, which allows cancer cells to migrate out of the primary tumor to form metastases." (PMID 30940778, 2019). "We aim to assess the diagnostic and prognostic usefulness of serum MMP-2 and TIMP-2 as potential biomarkers in comparison to well-established tumor markers of PC (CA 19-9, carbohydrate antigen 19-9 and CEA, carcinoembryonic antigen)." (PMID 30719232, 2019). "MMP-2 is a gelatinase and plays a key role in various tissue remodeling processes, including trophoblast invasion and tumor cell motility (Liotta, Steeg & Stetler-Stevenson, 1991)." (PMID 30729068, 2019). "Based on diagnostic sensitivity we indicated the advantage of TIMP-2 measurement over assessment of MMP-2 and classical tumor markers (CEA and CA 19-9) in the diagnosis of PC patients." (PMID 30719232, 2019). "In general, lumican seems to be a potent agent for the inhibition of tumor progression, which is interesting given that MMP-2 and MMP-9 expression has been reported as positively altered in ALL cases." (PMID 31437251, 2019). "In summary, our studies reveal a novel Sp1/E2F1/miR-203/Src pathway that is responsible for the activation of MMP2 and the tumor-promotive role of XIAP in BC cell invasion." (PMID 31811115, 2019). "It has also been described that MMP-19 is essential to the development of nasopharyngeal carcinoma due to its tumor suppressive and anti-angiogenic functions which can reduce secreted MMP-2 and VEGF." (PMID 31921634, 2019). "Mean values of MMP-2 expression in tumor for all degrees of organ staging (T2-T4) were lower in comparison to the expression assessed in the stroma." (PMID 31223594, 2019).
tumor (continued). "The serum activities of both MMP-2 and -9 in the tumor-induced mice were at higher levels compared to the normal group." (PMID 30787353, 2019). "Western blot analysis revealed that the expression levels of the protein MMP-9, MMP-2 and Vimentin in tumor tissues of YFTL treatment groups were noticeably lower than that in the MC group." (PMID 30781674, 2019). "DOX-MTX NP decreases the mRNA levels of MMP-2 (Matrix metalloproteinase-2) thereby preventing tumor invasion and metastasis." (PMID 31080743, 2019). "Serum levels of MMP-2 were elevated in PC patients with nodal involvement (N1 subgroup), presence of distant metastasis (M1 subgroup) and high depth of tumor invasion (T3 and T4 subgroups) in comparison to individuals from T2, N0 and M0 subgroups." (PMID 30719232, 2019). "The increased MMP2/TIMP2 ratio has been reported to exhibit direct correlation with advanced tumor stage, increased colorectal tumor invasion and poor prognosis." (PMID 30988064, 2019). "In vivo, the tumor growth and the expression of matrix metalloproteinase (MMP)-2/9 and KLF8 were also blocked by DANCR inhibition." (PMID 31827393, 2019). "Based on this function, MMP-2 is considered a crucial enzyme in the regulation of tumor proliferation and metastasis." (PMID 31088428, 2019). "The AUC for TIMP-2 (0.6037, p = 0.013) was higher than for MMP-2 (0.5624, p = 0.146), but lower than AUC for classical tumor marker (CA 19-9 – 0.8583, p < 0.001; CEA – 0.8790, p < 0.001) in the differentiation between PC patients versus healthy subjects." (PMID 30719232, 2019). "We previously observed the increased number of MMP-2 coupled CD31+ cells and CD68+ tumor associated macrophages (TAMs) at the invading front of ALTS1C1 tumors." (PMID 31106146, 2019). "MMP2, is a matrix hydrolase that specifically dissolves IV collagen in matrix metalloproteinase family; Its expression is positively correlated with tumor progression, metastasis, and poor prognosis." (PMID 31210752, 2019). "Treatment with C. ignea decreased the activity levels of MMP-2, and thereby reduced the possibility of tumor progression mediated by MMP-2." (PMID 31660294, 2019). "Taken together, these findings indicate that LLE inhibits tumor progression and angiogenesis through reduction of MMP-2 activity and VEGF level." (PMID 31842482, 2019). "In tumor tissue, the balance between TIMP2, MMP2 and MMP14 is tipped in favor of MMP14 and MMP2 suggesting that the levels of MMP2 activation in tumor tissue are increased." (PMID 31882975, 2019). "The overexpression of MMP-2 and MMP-9 is associated with pro-oncogenic events such as neo-angiogenesis, tumor cell proliferation, and metastasis." (PMID 31402861, 2019). "Nanotetrac also influences tumor invasion, angiogenesis, and metastasis via regulation of matrix metalloproteinase-2 (MMP-2) whose major function is blockage of STAT3 activation by the thyroid hormone." (PMID 31600974, 2019). "Matrix metalloproteinases (MMP)-9 and MMP-2 proteins can actively mediate the dissemination of tumor cells to distant sites." (PMID 31013639, 2019). "This process is often stimulated by tumor cell-derived proteases, such as thrombin, cathepsin B, cancer procoagulant (EC 3.4.22.26), MMP-2 and MMP-14." (PMID 30927923, 2019). "AKT signaling is known to regulate the expression of MMP-2/9 in several cancer cells and control tumor migration as well as invasion." (PMID 31717694, 2019). "It was shown that lower values of MMP-2 in tumor occurred in patients with a higher stage of metastasis to cervical lymph nodes (P=0.0150)." (PMID 31223594, 2019). "Upstream analysis and gene ontology isolated matrix metalloproteinase 2 (MMP2) as a potential candidate for promoting tumor progression after nicotine exposure (Bavarvaet al., 2013)." (PMID 32595938, 2019). "The level of MMP2 was significantly higher in tumor tissues and correlated with unfavorable clinical features and prognosis in GC." (PMID 31218131, 2019).
tumor (continued). "In turn, the increase of MMP-2 expression in stroma and its decrease in tumor occurs with the increasing degrees of regional staging; however, MMP-9 expression decreases in both locations with the increase of the N feature." (PMID 31223594, 2019). "According to the present study, there was a significant increase in MMP-2 gene fold expression in tumor cells with vascular invasion compared to control samples." (PMID 31582999, 2019). "The increased expression of MMP-2 and MMP-9 within tumor decreases the risk of metastases to cervical lymph nodes in the initial stage of the disease." (PMID 31223594, 2019). "Overexpression of MMPs particularly MMP-2 (Gelatinase A) and MMP-9 (Gelatinase B) has been associated with tumor progression, metastasis, and poor prognosis." (PMID 31817718, 2019). "In an angiogenic model of tumor progression, MMP2 was shown to play an important role in the development of an angiogenic phenotype." (PMID 30664713, 2019). "Given that MMP2 is the principal CTX receptor on the surface of tumor cells, the developed CTX-functionalized nanoplatform retains the flexibility to conjugate alternative diagnostic and therapeutic agents for different types of MMP2-overexpressing tumors." (PMID 30782154, 2019). "The invasion and metastasis of tumor cells is dependent on the degradation of the components of the extracellular matrix by MMPs, particularly MMP-2 and MMP-9." (PMID 31572058, 2019). "Because high expression of MMP-2, which functions as a key enzyme in tumor cell invasion, has been reported as a prognostic factor in NSCLC12, we next examined the effects of miR-130b on MMP-2 activity in miR-130b-overexpressing A549 cells." (PMID 31061410, 2019). "The protein contents of vascular endothelial growth factor (VEGF), matrix metalloproteinase (MMP)-2, and collagen IV in the serum and transplanted tumor and SDF-1α and CXCR4 in liver tissues were detected by enzyme-linked immunosorbent assay." (PMID 30789971, 2019). "The levels of MMP2 in blood vessels are also lower in benign neoplasms, and the percentage of activated MMP2 correlates with tumor size." (PMID 31466240, 2019). "The area under ROC curve (AUC) for TIMP-2 was larger than for MMP-2, but lower than for classical tumor markers." (PMID 30719232, 2019). "The finding that CLU reduces MMP-9 and MMP-2 expression by inhibiting NF-κB is biologically relevant for PCa because these enzymes play a role in tumor dissemination by degrading ECM and basement membrane." (PMID 31885575, 2019). "Taken together, the results demonstrated that miR-126 exerts tumor suppressing effects on the proliferation, migration and invasion by inhibiting MMP2, MMP9 and JAK2/STAT3 pathway via targeting ZEB1." (PMID 31007650, 2019). "Many studies have been published describing the relationship between MMP-2 expression and tumor angiogenesis." (PMID 31921634, 2019). "Overall, the results indicated that BA inhibits cell proliferation and induces apoptosis in the tumour tissues for inhibiting of Ki‐67 and MMP‐2." (PMID 30417527, 2019). "When the liposomal delivery system arrived at the tumor site, the matrix metalloproteinase-2 (MMP-2)-sensitive PEGylated PS cleaved the PEG shell at pH = 6.6." (PMID 31371782, 2019). "Subsequently, the protein expression level of N-cadherin, Vimentin, MMP-2 and MMP-9 associated with metastasis ability of tumor were detected to further determine the effect of different treatments." (PMID 31391034, 2019). "Since p21WAF1/Cip1 inhibits cyclin-Cdks, we were interested to see if hYSK1 also targets p21WAF1/Cip1 to excel tumor cell migration via activation of MMP-2." (PMID 30646538, 2019). "In RCCs, overexpression of MMP-1, MMP-2, and MMP-9 is linked to tumour stage, histological grade, progression, invasion of microvasculature, and distant metastasis." (PMID 31771219, 2019). "Berberine inhibits the release of MMP-2 from tumor cells and thus inhibits tumor cell destruction of the tissue matrix." (PMID 32009943, 2019).
tumor (continued). "MMP-2 is a key enzyme involved in the proteolysis of the major components of the basement membrane and is known to have a clear correlation with tumor invasion and metastasis." (PMID 31216681, 2019). "Studies on different types of solid tumors such as breast, bladder and pulmonary carcinomas reported that the activation of MMPs, especially MMP-2, is related to the tumor and/or the spread of cancerous cells." (PMID 29721201, 2018). "As the nanoparticles extravasated from the leaky areas of the tumor blood vessel, the nanoparticles shrank to 10 nm in response to overexpressed MMP-2 in the tumor environment, which improved the penetration ability in the matrix." (PMID 30340364, 2018). "Through the MEND strategy, this system can specifically target cancer cells responding to the up-regulated extracellular MMP-2 in tumours and provide enhanced cellular internalization via HA receptor-mediated endocytosis." (PMID 29410811, 2018). "In the presence of activated MMP-2, we found that accumulation of green fluorescence within the tumor cells was intense, and the green fluorescence accumulated not only into the cytoplasm, but also into the nucleoli." (PMID 29686590, 2018). "MMP-2 is a critical protease for tumor cell migration and invasion by degrading the extracellular matrix." (PMID 29385675, 2018). "Decreased MMP-2 expression together with increased epithelial cell marker expression by tumor cells decreases their ability to further disseminate." (PMID 30180883, 2018). "Studies revealed that MMP-9 is required for shift of angiogenic balance towards pro-angiogenic phase while MMP-2 contributes in tumor growth." (PMID 30344239, 2018). "The reduction in protein production corresponded to a reduced activity of MMP-2 and MMP-9, and demonstrated the “protective function” of Kisspeptin in term of cell change architecture and behavior associated to tumor recurrence." (PMID 29721201, 2018). "The TIMP2-based protein displayed selective binding capacity to the tumor tissues via the interaction with MMP-14/MMP-2." (PMID 29250984, 2018). "Metastasis process of the tumor was altered with the suppression in the expression of MMP-2, MMP-9 and urokinase-plasminogen activator (u-PA)." (PMID 30445746, 2018). "For tumor penetration, the size transition of the particles was actuated from 185.9 to 71.2 nm after incubating with MMP-2, and doxorubicin was released in a pH-dependent manner." (PMID 30340364, 2018). "MMP-2 can further facilitate angiogenesis of the tumor microenvironment by cleaving ECM molecules such as type IV collagen and coordinating with αvβ3 integrins." (PMID 29874869, 2018). "In vitro and in vivo studies in HepG2 cells and HepG2 tumour-bearing mice confirmed that overexpressed MMP2 protease in tumour tissue, together with intracellular glutathione, causes rapid release of doxorubicin, leading to inhibition of tumour growth." (PMID 30563158, 2018). "The increased CCL2 promoted an influx of CD11b+ monocytes into the primary tumor that also had increased matrix metalloproteinase (MMP)-2, MMP-3, and MMP-9 expression." (PMID 30458886, 2018). "Matrix metalloproteinase 2 (MMP-2) is often upregulated in tumor cells and plays a role in tumor cell migration and invasion by degrading the extracellular matrix." (PMID 30225259, 2018). "Most previous studies demonstrated that ATRA exerts inhibitory effects on the MMP-2 expression of various tumor types." (PMID 30225259, 2018). "Enhanced expression of MMP-2 was detected in several tumors and it strongly correlated with tumor stage and lymph node status." (PMID 29361917, 2018). "This type of remodeling has been associated with invasive CCs and overexpression of MMP-2 and MMP-9 is also correlated with a worse prognosis in patients with this tumor type." (PMID 29770331, 2018).
tumor (continued). "In an in vivo tumour model, it was shown that that the protein, mRNA expression and/or activity of MMP-2, MMP-3, MMP-7 and MMP-9 were significantly higher in UVB-exposed skin and tumours of IL-12 knockout mice compared with wild-type mice." (PMID 29555826, 2018). "The results were consistent with the idea that integrin-mediated signaling pathways are involved in regulation of MMP-2 expression and cell invasion in tumor cells." (PMID 29903032, 2018). "In this study, Curcumin reduced markedly the tumor volume, along with MMP-2 and MMP-9 activity in the tumor-bearing site, and the number of metastatic nodules in vivo in contrast to the untreated control group." (PMID 29890744, 2018). "Metalloproteinases, through the degradation of the extracellular matrix, play a crucial role in all these steps; consequently, a common strategy of tumor cells to trigger metastasis is the overexpression of metalloproteinases, mostly MMP-2." (PMID 29385675, 2018). "In this study, PTC patients with a high preoperative serum MMP-2 (≥86.30 ng/ml) were more likely to have a larger tumor size, presence of CLNM, LLNM, extrathyroidal invasion, and advanced TNM stage." (PMID 29949618, 2018). "As a MMP superfamily member, MMP2 is localized in a proteolytically active form on the surface of invasive cells, which has been found to play an important role in tumor invasion and metastasis." (PMID 29850505, 2018). "Out of these, MMP-2 and -9 which are synthesized and secreted in large amounts by tumor cells in a paracrine and/or autocrine manner, have been extensively studied." (PMID 30344239, 2018). "The intrahepatic tumour nodules were then evaluated for expression of E‐cadherin, Vimentin, Snail+Slug, MMP2 and Smad4 by immunohistochemical analysis." (PMID 29148232, 2018). "MMP expression, including that of MMP-2, is also elevated at the tumor–bone interface in response to osteoclast activity." (PMID 29874869, 2018). "The MMP-2 and -9 are collagenases involved in tumor invasion and metastasis through the degradation of collagen IV." (PMID 30518369, 2018). "In the present study, the presence of MMP-2 in tumour-invaded peritoneum was only seen in the proximity of inflammatory cells and vascular structures." (PMID 29623449, 2018). "Activated Stat3 regulates tumour invasion by regulating the gene transcription of matrix metalloproteinase 2 (MMP-2), MMP-9, TGF-β1 and β-catenin, which also decreased after treatment with MSC-CM." (PMID 30297887, 2018). "We proved, by gelatin zymography, that all tumour cell lines secrete significant amounts of pro‐gelatinases MMP‐2 and MMP‐9." (PMID 29517849, 2018). "Because the PI3K/AKT signaling pathway has been shown to increase tumor invasion and metastasis by regulating MMP-2 and MMP-9, we investigated the role of this pathway in SEMA5A-induced invasion." (PMID 29977159, 2018). "Results revealed a reduced expression of MMP2 in AQP1 siRNA‐treated tumours compared to CTRLs, indicating that reduced AQP1‐dependent vascularization is also cause of MMP2 reduced expression." (PMID 29044946, 2018). "miR-320a-PBX3 inhibits the active pathway of the MAPK and EMT and reduces the expression of dependent cytokinase 2 (CDK2) and MMP2 to inhibit tumor development." (PMID 29552328, 2018). "Previous reports suggested that the interaction between HMGB1 and RAGE triggered the activation of NF-κB, MAPK, and MMP-2/MMP-9 signaling pathways, which are associated with tumor growth, invasion, and metastasis." (PMID 29850505, 2018). "The secretion and activation of MMP2 and MMP9 are linked with the degradation of ECM and promotion of tumor metastasis." (PMID 29558998, 2018). "Previous studies have indicated that the expression of MMP-2 and MMP-9 are enhanced by radiation in a number of tumor types, and their expressions have been associated with poor prognosis." (PMID 30359388, 2018).